IL4 (interleukin 4)
Diseases named in the same sentence as IL4 in open-access papers (continued):
Sharing a sentence is not in itself a finding about the gene and the disease.
depression (continued). "Our data suggested that lower cytokine levels, especially IL-4, might be involved in the development of TA patients with depression." (PMID 38426163, 2024). "However, there are many inconsistencies in clinical studies on peripheral IL-4 levels between adolescent depression and healthy control." (PMID 38627683, 2024). "The authors confirmed that the lower level of eotaxin had a suggestive effect on TA patients with depression to a certain extent, which might be consistent with the declined IL-4." (PMID 38426163, 2024). "Even some studies showed a reduction of IL-4 in adolescent patients with depression." (PMID 38627683, 2024). "We found IL-4 to be increased in the AD with depression group in the superior frontal gyrus." (PMID 39526037, 2024). "Therefore, the first purpose of this study was to clarify the difference in peripheral RvD1, NLPR3, IL-1β, Il-18, and IL-4 between the adolescent patients with depression and the healthy control group." (PMID 38627683, 2024). "The evidence supporting the link between IL-4 and depression is conflicting." (PMID 39355088, 2024). "While markers such as IL-6, TNF-alpha, and CRP have well-established relationships with depression in cancer patients, the present study focuses on IL-4, BDNF, and neopterin due to their unique and potentially significant roles in the inflammatory and neurotrophic pathways." (PMID 39355088, 2024). "IL-4, MCP-1 and MIP-1β were higher in CSF from patients compared to controls, and could potentially be important to depression, although only IL-4 survived correction for multiple testing." (PMID 37016363, 2023). "For instance, the brain of depression animal models showed high levels of proinflammatory cytokines, and the intraventricular infusion of anti-inflammatory cytokine interleukin-4 (IL-4) might show antidepressant benefits by modifying central neurotransmitters." (PMID 36973813, 2023). "A 2016 study investigating the relationship between proinflammatory cytokines and major depression in cancer patients suggested the possibility that IL-1 may be a stronger predictor of “disease behaviours,” while IL-4 may be more specific to major depression." (PMID 38054202, 2023). "Relative gene expression changes in different inflammatory markers involved in allergic processes (TNFα, IL-1β, IL-4, IL-5, IL-6, and IL-13) were analyzed in the orbitofrontal cortex of suicide completers with a history of major depressive disorder (MDD) versus controls." (PMID 38069051, 2023). "Studies have shown that inflammatory factors IL-1β, IL-6, TNF-α, and CRP are elevated and anti-inflammatory factors IL-4, IL-8, and IL-10 are decreased in peripheral and cerebrospinal fluid and correlate with patients’ symptoms and disease duration in depression and anxiety." (PMID 36624089, 2023). "IL-4 might be protective against depression due to its ability to harness inflammation and to inhibit serotonin transporter activity." (PMID 35782423, 2022). "Besides, the baseline TNF-α level was significantly higher and IFN-γ, IL-4, and IL-2 were lower in patients with depression compared with the HC group." (PMID 35722555, 2022). "It was reported that mean levels of IL-1β, IL-4, IL-8 increase as depression became more severe." (PMID 35326343, 2022). "In addition, high estrogen release during PCOS increases interleukin 4 (IL-4), IL-1, IL-6, and interferon γ (IFN-γ) production and these increases are associated with depression-like symptoms in human and animal studies." (PMID 36117653, 2022). "Indeed, Increasing Arg1+ microglia in the hippocampus by enhancing IL4 signaling restored hippocampal neurogenesis and the resilience to stress-induced depression." (PMID 35782423, 2022). "Accordingly, this study intended to explore the association of Th1, Th2, and Th17 cells as well as their corresponding cytokines [including interferon (IFN)-γ, IL-4, and IL-17A] with anxiety, depression, and cognitive impairment in elderly gastric cancer patients." (PMID 36386524, 2022).
depression (continued). "In addition, a post-mortem study revealed that the expression of the anti-inflammatory cytokines IL-13 and IL-4 was increased in the orbitofrontal cortices of female and male suicide victims, who had been diagnosed with depression." (PMID 33672958, 2021). "After remission of depression, patients with BD had elevated IL-4 and TNF." (PMID 33946871, 2021). "Thus, our results suggest that the reduced IL-4 and IL-10 levels in serum with hippocampal M2 markers may be involved in the stress vulnerability after imipramine discontinuation, and the restoration and modulation of these factors may be useful to some forms of depression-associated conditions." (PMID 26521132, 2015). "Thus, our results propose potential of IL-4 and IL-10 to dampen elevated vulnerability to stress-related events to achieve more comprehensive treatment of depression." (PMID 26521132, 2015). "Additionally, IL-4 and IL-10 are suggested to play a significant role in affecting depression-like behaviors." (PMID 26521132, 2015). "However, we found that IL-4/10 alleviated depression-like behaviors that were observed in (co-Imi+CRS)+FS mice." (PMID 26521132, 2015). "Numerous studies have shown that higher IL4 levels are protective for depression." (PMID 23049769, 2012). "Studies suggest that IL-4 may play a role in regulating the immune response to cancer cells, but its influence on the psychological well-being of cancer patients, particularly in relation to depression, is complex." (PMID 39355088, 2024). "Besides alterations that are closely related to innate-immune mediated inflammation, the adaptive immunity-associated inflammatory cytokine, IFN-γ, has also been implicated in the pathogenesis of depression, with increased expression of serum IFN-γ/IL-4 ratio in MDD patients." (PMID 39763658, 2024). "It suggests that IL-4 may play an important part in the development of depression in TA patients." (PMID 38426163, 2024). "However, studies comparative to ours exploring CSF IL-4 in other subgroups of patients with depression, e.g., patients with treatment resistant depression or recurrent depression could elucidate this theory further." (PMID 37016363, 2023). "Thus, the finding of increased levels of CSF IL-4 among patients with recent-onset depression could perhaps reflect an early protective mechanism against the pro-inflammatory alterations seen in the blood." (PMID 37016363, 2023). "IL-4 is an important cytokine that helps in higher brain functions, such as memory and learning; IL-1β, which we also found increased during infection, has been suggested to exert a negative effect on cognitive behavior, characterized by sickness, depression, and stress." (PMID 32635653, 2020). "Results of a decreased IL-4-responsiveness of microglia as well as the inhibition of IL-10-signaling leading to depression-like behavior in animal models of depression demonstrate the need for further investigations on the role of anti-inflammatory agents in depression." (PMID 30524320, 2018). "Moreover, contrary to most of the proinflammatory cytokines analyzed in this work (except IL-15), which seem to have promoting effects towards depression, IL-4 appears to have beneficial effects upon psychiatric disorders in addition to the obvious anti-inflammatory effects." (PMID 30662368, 2018). "Furthermore, as TNFα and IL4 are also markers of Th1 and Th2 immune pathways respectively, this study suggests a shift away from Th1 responses in favour of Th2 responses, which is in line with previous studies of patients recovering from depression." (PMID 26974430, 2016). "Thus, we propose that IL-4 and IL-10 may be able to lower the vulnerability to some forms of stress- and depression-related conditions after imipramine discontinuation." (PMID 26521132, 2015).
depression (continued). "Escitalopram can reduce the levels of pro-inflammatory cytokines—IL-1β, IL-1ra, IL-2, IL-4, IL-6, IL-8, IFN-y, TNF-α in the serum of patients suffering from depression, while simultaneously increasing the level of anti-inflammatory IL-10." (PMID 41302150, 2025). "We observed significantly elevated serum TNF-α, IL-4, and IFN-γ levels in adolescents with depression." (PMID 39980978, 2025). "The single intranasal administration of recombinant IL-4 (1 ng/mouse) decreased endogenous IL-4 in the HPC, increased IL-4 in the PFC, and ameliorated depression-like behaviors through the modulation of neuroinflammation and oxidative stress." (PMID 38791125, 2024). "Reduced levels of cytokines such as IL-10, IL-4, and TGF-β1 have been observed in both the plasma of patients with depression and the brain tissue of animal models of depression." (PMID 38916735, 2024). "In conclusion, the present study suggests a potential link between elevated neopterin levels, decreased IL-4, and BDNF levels, and the presence of depression in lymphoma patients receiving R-CHOP chemotherapy." (PMID 39355088, 2024). "In the superior frontal gyrus medial segment, IL-4 was higher in AD + MDD group (0.028 ± 0.011) compared to AD only (0.022 ± 0.008) (F1, 34 = 4.186, p = 0.049), suggesting that the co-morbidity depression in AD may induce an anti-inflammatory environment." (PMID 39526037, 2024). "For instance, a study on adolescent patients with the first-episode of depression highlighted a correlation between pro-inflammatory TNF- and IL-6 signaling and increased anti-inflammatory activity mediated by IL-10 and IL-4." (PMID 38912378, 2024). "The results revealed that depression patients’ plasma levels of CCL2, IL-6, IL-4 and IL-10 were all positively correlated." (PMID 37575572, 2023). "IL-4, MCP-1 and MIP-1β have only been investigated in few prior studies in the context of depression." (PMID 37016363, 2023). "Regarding peripheral blood levels, meta-analyses found lower levels of serum IL-4 in patients with depression and lower levels of serum MIP-1β in patients with depression compared to controls." (PMID 37016363, 2023). "The levels of IL-4, IL-10, T, and NPY in depression patients, DCMI patients, and CUMS + LPS model rats elevated, while the levels of IL-1β, IL-6, and TNF-α were reduced." (PMID 35432561, 2022). "This meta-analysis included 22 eligible studies of 827 patients with major depressive disorder (MDD): seven studies for IL-1β, 15 for IL-6, 11 for TNF-α, six for IL-4, and four for interferon-γ." (PMID 35280153, 2022). "Differences in the cytokine profile between BD and MDD were also confirmed by using machine learning—higher levels of IL-10, IL-4 and thiobarbituric acid reactive substances (TBARS) proved to be good at distinguishing between bipolar disorder from unipolar depression." (PMID 36294388, 2022). "Meta-analyses and systematic reviews show that levels of IL-1β, IL-2, IL-4, IL-8, the soluble IL-6 receptor (sIL-6R), IL-5, CCL3, IL-17A, and TGF-β1 are significantly changed in depression." (PMID 36614020, 2022). "In in vitro and in vivo models of depression, BDNF was shown to improve depressive-like behavior by upregulating anti-inflammatory cytokine IL-10, IL-4, and TGF-β1 and downregulating the pro-inflammatory cytokine IL-1β, IL-17, and TNF-α." (PMID 32256638, 2020). "Moreover, the observed increases in both IFN-γ: IL-4 and TNF-α: IL-4 ratios in the SA and SA + SD groups suggest that an inflammatory process takes place in vulnerable subjects with severe anxiety, becoming conspicuous as depression emerges in women displaying severe depression." (PMID 30943938, 2019). "In this study, we aimed to explore the role of IL-2, IL-4, IL-12, TNF-α, TGF-β1, and MCP-1 in major depression and to investigate the effects of sertraline therapy." (PMID 18317531, 2007).
depression (continued). "Our results suggest that the proinflammatory cytokines (IL-2, IL-12, and TNF-α) and MCP-1 were significantly higher, whereas anti-inflammatory cytokines IL-4 and TGF-β1 were significantly lower in patients with major depression than those of healthy controls." (PMID 18317531, 2007). "Evidence also indicates that in patients with major depressive disorder (MDD), levels of inhibitory cytokines (including IL‐4, IL‐10, and IL‐12p70) are decreased, while neurotoxic cytokines (including CCL5) are relatively elevated, and oxidative stress levels are increased." (PMID 41583906, 2026). "Individuals with depression exhibited significantly elevated levels of IL - 6 and a reduced IL - 2/IL-4 ratio compared to non-depressed participants." (PMID 41000397, 2025). "The other cytokines measured—IL-1β, IL-4, IL-10, and TNF-α—showed little variation throughout the different phases, indicating their minimal involvement in the mediation of depression." (PMID 40564108, 2025). "In a recent study conducted with adolescents with depression, it was possible to see a significant increase in some markers such as IL-4 and Treg + Th2, which have not been observed in most studies conducted with adults." (PMID 38474387, 2024). "Depression patients with suicidal attempts have high levels of blood pro-inflammatory cytokines such as TGF-β, CRP, and decreased levels of anti-inflammatory cytokines such as IL-4." (PMID 38459460, 2024). "Targeting biomarkers such as neopterin, IL-4, and BDNF may help in the management of depression in lymphoma patients undergoing chemotherapy." (PMID 39355088, 2024). "The second major finding is that, as with non-pregnancy-related MDD, prenatal depression severity is linked with greater IRS vs. CIRS responses, despite the presence of a robust Th-2 response and elevated IL-4 levels." (PMID 37239199, 2023). "A previous study identified increases in serum cytokines associated with innate immune activation in FEP when compared to healthy controls; however, TNF-α and IL-4 were elevated further in FEP patients with depression compared to those without depression." (PMID 36463221, 2022). "This may show that in the case of IL-4, PTSD alone has a greater impact on increased serum levels of this cytokine compared to patients with depression concomitant with PTSD." (PMID 35326343, 2022). "The investigation of 38 depression studies found that monocyte-derived, and other inflammatory cytokines (IL-1, IL-4, IL-6, and TNF) were significantly overexpressed in individuals with depression, while T cell derived cytokines (IL-10, and INF-γ) were uncorrelated with depression." (PMID 36206293, 2022). "IL4‐driven microglia, characterized by high expression of Arg1, in the hippocampus trigger BDNF‐dependent neurogenesis, which is a response to chronic stress and a protection against depression‐like behaviors." (PMID 34878231, 2022). "To investigate the differences in the expression of inflammatory factors in the serum of normal person, patients with depression, and patients with DCMI, we performed ELISA to detect the levels of NPY, T, IL-1β, IL-6, TNF-α, IL-10, and IL-4 in the peripheral blood plasma." (PMID 35432561, 2022). "IL-4-driven Arg1+ microglia in the hippocampus trigger brain-derived neurotrophic factor (BDNF)-driven neurogenesis in reaction to stress, resulting in improved resilience to stress-induced depression." (PMID 36614020, 2022). "Decreases in IL-2, IL-4 productions, and CD4 percentage were strictly independent of anxiety and depression rates, as there were no more significant differences between the two groups given the HADS scores for anxiety and depression." (PMID 34987425, 2021). "An increase of two well-known pro-inflammatory cytokines, called interleukin (IL)-1β and tumor necrosis factor-α (TNF-α), as well as a decrease of anti-inflammatory cytokines (e.g., IL-10, IL-4, and TGF-β1) have been observed in hippocampus and cortex of animal models of depression and MDD patients." (PMID 32435223, 2020).
depression (continued). "We therefore examined the effects of Aβ1-42 oligomers i.c.v. injection on the mRNA levels of pro-inflammatory cytokines (IL-1β and TNF-α) and anti-inflammatory cytokines (IL-4 and TGF-β1) in the hippocampus, a brain area of primary relevance in the pathogenesis of depression." (PMID 31293421, 2019). "In addition, resveratrol supplementation reduces levels of pro-inflammatory cytokines (IL-1β, IL-2, IL-4, IL-6, TNF-α) in animal models of depression." (PMID 30200269, 2018). "These meta-analyses showed additionally that Th2 and Tregulatory (Treg) cytokines (including IL-10, IL4, and IL-5) were not significantly altered in major depression indicating that major depression is characterized by M1 and Th1 activation." (PMID 29103192, 2018). "In this study, we observed increased levels of proinflammatory cytokines of IL-6, IL-1β, TNF-α as well as anti-inflammatory cytokines of IL-4 and IL-10 in the rats with depression-like phenotype, but not rats without depression-like phenotype." (PMID 28600519, 2017). "Even though the combination of IL-4/10 itself did not have an antidepressant effect, it prevented depression-like behaviors in the co-Imi+CRS mice that were exposed to additional stressor after imipramine washout." (PMID 26521132, 2015). "However, IL-13 was proven only one-tenth of the inhibiting effect of IL-4 in RA, without a direct correlation with depression." (PMID 38426163, 2024). "Clinical studies have found that compared with normal people, patients with depression have proinflammatory cytokines such as tumor necrosis factor-α(TNF-α)、Interleukin-1β(IL-1β)、IL-6 and interferon While anti-inflammatory cytokines such as IL-10, IL-4, IL-8 and transforming growth factor." (PMID 37167313, 2023). "Furthermore, IL-6, tumor necrosis factor-alpha (TNF-α), and IL-1β are implicated in the pathophysiology of depression, and individuals with depression often have elevated circulating IL-1β, IL-6, and TNF with reduced levels of interferon-gamma (IFN-γ), IL-10, and IL-4." (PMID 35546876, 2022). "first reported the association of cytokine polymorphisms with PSD, showing that patients with polymorphisms of anti-inflammatory cytokines IL-4 and IL-10 rather than pro-inflammatory cytokines TNF-α, IL-1β, IL-6 and IL-8 had an increased propensity to develop depression in the acute phase of stroke." (PMID 36225923, 2022). "In addition, patients with unipolar depression and healthy controls also showed an AUC of 0.74, with 0.69 sensitivity and 0.70 specificity using seven variables (IL-6, carbonyl, BDNF, IL-10, IL-17A, IL-4, and TNF-α)." (PMID 33578686, 2021). "Furthermore, increased IL-6 as well as decreased interleukin-4 (IL-4) and albumin in serum discriminate MS patients with from those without depression." (PMID 34764926, 2021). "In major depression with atypical features, lowered IL-4 but increased IL-2 concentrations were observed, whereas no changes in IL-6 or TNFα concentrations could be established." (PMID 29103192, 2018). "Similar to the findings in CP/CPPS patients, elevated levels of IL-1α, IL-1β, IL-4, IL-13, and TNF-α were observed in CP/CPPS rat prostates, and these elevated cytokine levels showed a positive trend in their correlation with anxiety, depression, and memory impairment." (PMID 27334333, 2016). "The present study revealed a significantly decreased IL-4 levels following cycles of chemotherapy and a negative correlation with PHQ-9 scores align with studies suggesting that major depression in cancer patients may be linked to inadequately controlled inflammation related to the disease." (PMID 39355088, 2024). "Similarly, to IL-1β and IL-8, the analysis of IL-4 demonstrated that its concentration levels increased as depression became more severe, regardless of whether with or without concomitant PTSD." (PMID 35326343, 2022).